INS (insulin)
Diseases named in the same sentence as INS in open-access papers (continued):
Sharing a sentence is not in itself a finding about the gene and the disease.
prediabetes (continued). "For individuals with T2DM or prediabetes, cornelian cherry supplementation could be an adjunct therapy for improving glycaemic control and insulin sensitivity, potentially reducing the need for medication or enhancing its effectiveness." (PMID 38999920, 2024). "In addition, “expression,” “lifestyle interventions,” “insulin sensitivity,” “prevalence,” and “children” have continuously been the research focus of prediabetes (Q = 0.4333, S = 0.683)." (PMID 38241546, 2024). "In keeping with our finding, a meta-analysis concluded that prediabetes (representing another insulin resistant condition of confined severity) did not associate with the risk of breast cancer." (PMID 39497166, 2024). "Most importantly, participants with T2D in our study had better glycemic control and the participants without T2D were less healthy from a metabolic perspective, being predominantly obese, insulin resistant, and having fasting glucose in the range of prediabetes." (PMID 37708362, 2024). "Prediabetes in our girls is driven by poor insulin secretion and poor β cell function." (PMID 39055387, 2024). "Thus, interventions to reduce liver fat have the potential to improve insulin regulation in prediabetes, while the normalization of glycemia has been associated with health benefits and reduced incidence in related comorbidities." (PMID 39767255, 2024). "Additionally, a double-blind crossover study found that taking 30 g of inulin daily for 2 weeks improved insulin sensitivity in individuals with prediabetes compared to a control group." (PMID 39458444, 2024). "We conclude that PAK1 is essential for muscle mitochondrial function, and it is mediated through a p38MAPK/ATF2/PGC1α-axis signaling pathway, providing a new signaling cascade for potential therapeutic interventional strategies to skeletal muscle insulin resistance in prediabetes and T2D." (PMID 37759961, 2023). "This may have resulted in higher biological variation in insulin secretion and glucose serum levels, which is consistent with what has been reported in humans with prediabetes." (PMID 37237932, 2023). "Evidence also shows that prediabetes may be involved with reduction in insulin sensitivity, dysfunction of pancreatic beta cell, and further promotion of atherosclerosis." (PMID 36639363, 2023). "In addition, it is necessary to evaluate the impact of skipping breakfast on prediabetes in other races to generalize our findings because there are racial differences in insulin sensitivity and insulin response." (PMID 36909337, 2023). "In conclusion, based on the evidence analyzed from the randomized control trials, there is insufficient evidence supporting a potential beneficial effect of vitamin E supplementation on improving HbA1c, fasting glucose, and insulin concentrations in subjects with prediabetes." (PMID 38068801, 2023). "In prediabetes, insulin secretion increases to compensate for the emergence of insulin resistance." (PMID 37288300, 2023). "A previous study reported that Yijinjing, traditional Chinese exercise combined with resistance training, could improve fasting blood glucose, insulin resistance, and reduce liver fat in middle-aged and older people with prediabetes." (PMID 38004306, 2023). "The stages were as follows: prediabetes, T2D, T2D with insulin treatment, and T2D remission." (PMID 36607714, 2023). "A 5-week randomized crossover trial of eTRE in men with prediabetes showed improved insulin levels, insulin sensitivity, blood pressure, and oxidative stress for the eTRE group, even though the participants received enough food to maintain their weight, and no weight loss occurred." (PMID 38002621, 2023). "We investigated associations between different types of carbohydrates, including fermentable oligosaccharides, disaccharides, monosaccharides, polyols (FODMAPs), and polysaccharides (dietary fibre), and body composition and glucose/insulin responses in subjects with prediabetes." (PMID 38140329, 2023).
prediabetes (continued). "Besides, a recent study showed that 10 weeks of NMN administration in doses of 250mg/d improved skeletal muscle insulin sensitivity and insulin signaling in women with prediabetes." (PMID 36777361, 2023). "In conclusion, our findings suggest that long-term almond consumption may negatively affect insulin sensitivity and glucose metabolism in subjects with prediabetes." (PMID 37258943, 2023). "For instance, individuals with prediabetes may still have a pancreas capable of producing a sufficient amount of insulin to maintain normal fasting BGL, but their daily BGL may fluctuate in a big range depending on diet and lifestyle." (PMID 37892937, 2023). "Indeed, the relationship between insulin/glucose and prediabetes is considered direct (inadequate insulin secretion and inefficient insulin sensitivity of the liver, which fails to downregulate glucose levels)." (PMID 37400796, 2023). "Regarding vitamin E, based on the evidence from the randomized controlled trials analyzed, there is insufficient evidence supporting a potential beneficial effect of vitamin E supplementation on improving HbA1c and fasting glucose and insulin concentrations in patients with prediabetes." (PMID 38068801, 2023). "Additionally, the ORs for prediabetes, high insulin and high HOMA-IR were significantly lower for the participants in higher STf, tertiles, with ORs of 0.53 (95% CI: 0.34; 0.82), 0.48 (CI 95: 0.28; 0.82) and 0.37 (95% CI: 0.22; 0.64), respectively." (PMID 37819420, 2023). "Moreover, the in vitro models (rat cell line: L6.GLUT4myc, and human cell line: LHCN-M2) used to study muscle physiology under insulin-resistant conditions have provided invaluable insights into the intracellular mechanisms operating in prediabetes." (PMID 37759961, 2023). "Insulin itself vasodilates skeletal muscle so that insulin-induced microvascular flow increases its tissue delivery, as well as the delivery of nutrient substrates in the prediabetes stage." (PMID 37810890, 2023). "In contrast, an RCT including obese individuals with prediabetes reported an increase in insulin sensitivity index assessed with a hyperglycaemic glucose clamp, during treatment with sildenafil 25 mg for three times daily compared to placebo in a parallel design study over three months." (PMID 37256099, 2023). "Thus, during prediabetes, high free-fatty acid levels produced by lipolysis in adipose tissues promoted lipotoxicity and insulin resistance, whereas exercise promoted lipolysis and directly oxidized IMAT resulting in fat reduction in thigh muscles." (PMID 37899436, 2023). "Interestingly, in our study, insulin sensitivity in those with prediabetes as well as with T1D significantly increased over six years with concomitant increases in dietary fiber." (PMID 37960272, 2023). "At the end of follow-up, insulin sensitivity improved in patients in whom prediabetes reverted and remained stable in those with persistent prediabetes: 0.09 [0.08–0.11] versus 0.04 [0.01–0.07], p = 0.001 (Stumvoll index); 6.5 [6.0–12] versus 2.8 [2.4–5.3], p = 0.002 (Matsuda index)." (PMID 37202497, 2023). "Beta cells could be an especially sensitive target in prediabetes and related conditions, because not only do they produce insulin, but also respond to insulin and glucose levels themselves." (PMID 36815184, 2023). "Also, insulin sensitivity improved with the reversibility of prediabetes, compared to those with persistent prediabetes: 0.09 [0.08–0.11] versus 0.04 [0.01–0.07], p = 0.001 (Stumvoll index)." (PMID 37202497, 2023). "We reported that genistein could prevent prediabetes by improving hepatic function and also suggest that the activation of hepatic insulin signaling contributes to the beneficial effects." (PMID 36570152, 2022). "However, the percent changes were similar in extent to insulin-resistant individuals and those with prediabetes." (PMID 35851317, 2022).
prediabetes (continued). "Therefore, the aim of this study was to determine the effect of finger millet muffin consumption on postprandial GR, insulin response (IR), GE and satiety in healthy individuals and individuals with prediabetes." (PMID 35603664, 2022). "It is not yet known whether millet-based products will exert an attenuating effect on blood glucose and insulin levels in individuals with prediabetes." (PMID 35603664, 2022). "Consequently, the C-peptide response at 120 min post-OGTT was clearly higher in prediabetic individuals than in NGT individuals, showing that post-OGTT pancreatic insulin release is augmented in prediabetes." (PMID 35190847, 2022). "More interestingly, a 10 week, randomized, placebo-controlled, double-blind trial to evaluate the effect of NMN supplementation in postmenopausal women with prediabetes has shown NMN increases muscle insulin sensitivity and insulin signaling in prediabetic women." (PMID 35057482, 2022). "Besides, restricted cubic spline models showed linear dose–response relationships between DII and the odds of insulin resistant and prediabetes." (PMID 35250879, 2022). "Interestingly, we previously reported that circulating miR-195-5p and miR-7-5p were reduced by short-term intensive insulin therapy in subjects with early T2D and vitamin D supplementation in subjects with prediabetes, respectively." (PMID 36120427, 2022). "Since insulin exhibits its effect through its receptor, we investigated the gene expression of the insulin receptor (IR), which was found to be 1.18-fold higher in prediabetes cases and 0.85-fold in the newly diagnosed T2D group compared to the control group." (PMID 36004027, 2022). "Early time-restricted feeding improves insulin sensitivity, blood pressure, and oxidative stress even without weight loss in men with prediabetes." (PMID 36017220, 2022). "Furthermore, Lactulose has prebiotic effects that have been proven to reduce fasting and postprandial glucose and inflammation markers and improve insulin sensitivity and lipid profile in subjects with prediabetes." (PMID 36187096, 2022). "In their study, they found that eTRF could improve appetite, oxidative stress, cell responsiveness, blood pressure, and insulin sensitivity in men with prediabetes." (PMID 36017220, 2022). "However, dysregulation of α‐cell function in prediabetes occurs early and independently of changes in β‐cells, which suggests insulin having a less significant role on glucagon control." (PMID 35822422, 2022). "A randomized, double-blind trial enrolling 40 patients with prediabetes showed that an 8-week treatment with empagliflozin was able to restore brain insulin sensitivity compared with placebo, which may contribute to the beneficial effects of SGLT-2 inhibitors." (PMID 36482415, 2022). "This pilot study analyzed the efficacy of a nutritional intervention based on the Mediterranean diet in comparison with a healthy standardized diet to reduce HbA1c and insulin levels and, therefore, reduce the prevalence of prediabetes in a rural pediatric population." (PMID 36079871, 2022). "Increasing the concentration of CRP in prediabetes may reduce insulin sensitivity and eventually worsen glycemic status by raising blood sugar." (PMID 35659064, 2022). "In this study, they could improve appetite, oxidative stress, cell responsiveness, blood pressure, and insulin sensitivity in men with prediabetes." (PMID 36017220, 2022). "However, prediabetes presents overlapping pathophysiology of impaired insulin sensitivity and secretion." (PMID 36118835, 2022). "Only one study has, so far, focused on weight loss intervention in subjects with both prediabetes and obstructive sleep apnea, showing that changes in SpO2 were associated with changes in insulin sensitivity but not with weight loss." (PMID 35268504, 2022).
prediabetes (continued). "However, in individuals with reduced insulin sensitivity, as is the case in prediabetes, the postprandial effect of insulin is impaired, leaving the circulating free fatty acids (FFA) elevated." (PMID 34827678, 2021). "A 10-weeks, randomized, placebo-controlled, double-blind trial demonstrated that NMN (250 mg/day) supplementation only increased muscle insulin sensitivity, insulin signaling, and muscle remodeling in women with prediabetes who are overweight or obese (NCT03151239)." (PMID 34867355, 2021). "Sutton and colleagues found that a 5-week of 8-h early time restricted feeding improved insulin levels, insulin sensitivity, b cell responsiveness, blood pressure, and oxidative stress levels in men with prediabetes even though food intake was matched to the control arm and no weight loss occurred." (PMID 33435416, 2021). "We examined the effects of astaxanthin supplementation for 12 weeks on glucose metabolism, glycemic control, insulin sensitivity, lipid profiles and anthropometric indices in healthy volunteers including subjects with prediabetes with a randomized, placebo-controlled trial." (PMID 34959932, 2021). "The lowered blood glucose concentration observed in the exercising prediabetes animals may be due to increased GLUT4 translocation via the action of insulin." (PMID 33888141, 2021). "In addition to this, the participants with prediabetes also showed reductions in fasting insulin, insulin secretion over 2 h in response to an oral glucose tolerance test (OGTT) and an increase in both insulin sensitivity and HDL." (PMID 33449916, 2021). "Dyslipidaemia often occurs in prediabetes and may gradually impair insulin signaling and function, and therefore is an important endpoint measurement in interventions." (PMID 34835989, 2021). "A lower insulin sensitivity combined with insufficient insulin secretion, measured as a lower disposition index (DI), is an independent predictor of the conversion of prediabetes to T2D across many ethnic groups and races." (PMID 33527668, 2021). "Data are dispersed, and the question remains whether prediabetes is characterized by reduced myocardial insulin sensitivity." (PMID 34827678, 2021). "The intercorrelation between the immune system, EOS, and insulin in prediabetes was confirmed." (PMID 34099024, 2021). "We thereby suggest that nutrition modulation, including vitamin D, iodine, and other elements related to glucose homeostasis and insulin sensitivity, plays a vital and objective role in the occurrence and development of prediabetes or T2DM in Chinese individuals." (PMID 33817307, 2021). "In the intraperitoneal glucose tolerance test (ipGTT) at six weeks, NRs on the Chow diet displayed a moderate impairment in glucose tolerance (overall p < 0.05) and a marked increase in insulin secretion (overall p < 0.001), which confirms the presence of prediabetes in this model." (PMID 33401592, 2021). "Indeed, 150 min/week of moderate intensity is considered beneficial in adult individuals with prediabetes, improving insulin sensitivity." (PMID 34684345, 2021). "Combined with longitudinal imaging of beta cell mass, these results demonstrate that alterations in beta cell function and efficacy in terms of glucose-induced insulin release prevail over the increase in beta cell mass to compensate for insulin resistance in HFD-induced prediabetes." (PMID 33967961, 2021). "We examined associations of circulating plasma levels of MR-proANP, copeptin, CT-proET-1 and MR-proADM with incident T2D, the combined endpoint of incident prediabetes/T2D and with fasting and 2 h-glucose, fasting insulin, HOMA-IR, HOMA-B and HbA1c at follow-up." (PMID 33066780, 2020). "Additionally, the KEGG pathway enrichment analysis confirmed that insulin secretion is involved in the development of T2DM in prediabetes patients." (PMID 32664305, 2020).
prediabetes (continued). "This study aimed to identify a better predictor for the incidence of prediabetes, which we hypothesize to be the triglyceride-glucose (TyG) index, a simplified insulin resistance index." (PMID 33059672, 2020). "Although the authors of this study did not provide information on the total number of humans meeting the criteria for prediabetes, some of those insulin-resistant participants had prediabetes according to their HbA1c and 2-hour plasma glucose levels after a 75-g OGTT." (PMID 31838512, 2020). "Thus, VAT/m3 has been shown to have a significant better correlation with markers of insulin sensitivity and prediabetes than uncorrected VAT volume." (PMID 32664590, 2020). "Together, this study identified a novel role for miR-27 in regulating insulin signaling and these findings suggest that targeting of miR-27 may be a potential approach to increase insulin sensitivity in obese people in prediabetes stage." (PMID 33212990, 2020). "Among pubertal obese children in this study, comparable IGI and HOMA-β between those with normal and prediabetes HbA1c may reflect an impairment of first-phase insulin secretion in children with prediabetes HbA1c, which is similar to patients with IFG and IGT." (PMID 33224197, 2020). "The increase in mean IGFBP-1 and adiponectin levels 1 year after RYGB to normal levels suggest reduced hepatic inuslin resistance, improved insulin sensitivity and protection against future prediabetes and/or T2DM in those with normal glucose levels and prediabetes." (PMID 32934313, 2020). "Future studies are needed to investigate whether rhythmicity in DAG is functionally related to insulin sensitivity and how this might be altered in prediabetes." (PMID 32272236, 2020). "Importantly for this study, the CAF group demonstrated glucose and insulin derangements consistent with prediabetes." (PMID 32872256, 2020). "We hypothesized that, in Asian Indian women with prediabetes, supplementation of vitamin D could lead to decrease in glycemia and reversal of prediabetes to normal glucose regulation, along with improvement in insulin sensitivity and body composition." (PMID 31937856, 2020). "In addition to being down-regulated in individuals with prediabetes, hsa-miR-144-5p also correlated inversely (pc < 0.05) with insulin levels and the HOMA2 index." (PMID 31222113, 2019). "However, for those with prediabetes, VD supplementation has been shown to improve insulin sensitivity." (PMID 31141980, 2019). "Here we demonstrated that TdGSH eliminated the detrimental effects of LOsG on GT and kept the fast plasma insulin level at normal levels, and thus could prevent the glucotoxicity-induced occurrence of prediabetes." (PMID 30975975, 2019). "People with prediabetes had higher fasting insulin (P = 0.03) than those with NGT." (PMID 30857250, 2019). "However, it has been reported that supplementing exercise with MTF (but not exercise alone), lowered proinsulin concentrations and increased insulin clearance in adults with prediabetes suggesting a synergistic effect of both treatments." (PMID 31814870, 2019). "We still do not have a systematic understanding of how healthy individuals and those with prediabetes differ at baseline or change over time or in response to stresses such as viral infections, and whether such responses depend on insulin-resistance status." (PMID 31142858, 2019). "Moreover, the evidence linking milk and, in particular, calcium intake, insulin secretion and sensitivity has been related to glucose homeostasis in both prediabetes and T2D." (PMID 30884820, 2019). "During periods of prolonged sitting, adults with prediabetes may have more beneficial postprandial insulin responses to a low-energy first meal." (PMID 29882811, 2018). "A limitation of the current study is that we made use of the radiotracer [18F] FDG, so may have underestimated the metabolic activity of insulin-resistant tissues in individuals with prediabetes." (PMID 30145664, 2018).